MYCN (MYCN proto-oncogene, bHLH transcription factor)
Diseases named in the same sentence as MYCN in open-access papers (continued):
Sharing a sentence is not in itself a finding about the gene and the disease.
neuroblastoma (continued). "PRMT5 inhibition using GSK3326593 led to a significant improvement in survival in the Th-MYCN neuroblastoma mouse model and excellent target engagement was observed with strong SDMA reduction." (PMID 39313128, 2024). "Integrating of genetic features with chemosensitivity data revealed a robust correlation between MYCN amplification and sensitivity to bromodomain inhibition in pediatric cancer neuroblastoma." (PMID 39273015, 2024). "Here, we tested four different protocols that are used to generate tNCC and SA cells to evaluate how different protocols can influence producing MYCN-driven neuroblastoma." (PMID 39367051, 2024). "We leveraged this model to uncover mechanisms by which ALK and MYCN cooperate in the pathogenesis of neuroblastoma." (PMID 38451815, 2024). "The SAGA complex scored among the top enriched epigenetic complexes in MYCN-amplified neuroblastoma." (PMID 38820154, 2024). "Altogether, these results provide evidence for RUNX1T1 being required to maintain a MYCN-driven ESC-like phenotype characteristic of aggressive MYCN-amplified neuroblastoma." (PMID 38992040, 2024). "Addition of 4-OHT had little effect by itself, but greatly enhanced the inhibitory effect of depletion of each subunit, suggesting that TFIIIC has both general and MYCN-specific roles in neuroblastoma cell proliferation." (PMID 39177021, 2024). "The MYCN gene amplification status of neuroblastoma specimens was called with 88% accuracy overall, with > 0.5 prediction probability." (PMID 39169157, 2024). "MYCN-amplified neuroblastoma (MNA neuroblastoma) represents about half of poor prognosis neuroblastoma, with the remainder attributable to enhancer alterations leading to over-expression of TERT or MYC." (PMID 39313128, 2024). "Relapsed neuroblastoma exhibiting both ALK mutation and MYCN amplification is regarded as a clinically challenging high-risk patient group with low survival rates." (PMID 38858548, 2024). "XRN2 expression was found to be induced by direct binding of MYCN to its promoter region in neuroblastoma cells, and two members of the let-7 family (let-7c and let-7g) were thus significantly upregulated in XRN2-depleted neuroblastoma cells." (PMID 38689093, 2024). "Genetic deletion of H2afy in MYCN-driven neuroblastoma cells reverts in vivo resistance to PD-1 blockade by eliciting activation of the adaptive and innate immunity." (PMID 39255035, 2024). "AURKA prevented the Fbxw7-mediated degradation of MYCN, which facilitated the growth of MYCN-amplified neuroblastoma cells." (PMID 38287009, 2024). "RNA sequencing of three MNA neuroblastoma lines treated with GSK3203591 reveal deregulated MYCN transcriptional programmes and altered mRNA splicing, converging on key regulatory pathways such as DNA damage response, epitranscriptomics and cellular metabolism." (PMID 39313128, 2024). "Together, these data nominate the SAGA complex as a selective dependency in MYCN-amplified neuroblastoma for further investigation." (PMID 38820154, 2024). "Our study consolidates and extends the links previously made between MYCN activity in neuroblastoma and spliceosomal vulnerability." (PMID 39313128, 2024). "We previously found that JMJD6 is essential for the survival of neuroblastoma cells (including MYCN-amplified and MYC-overexpressed cells), which was further validated by an independent study, indicating that neuroblastoma has JMJD6 dependency." (PMID 38488852, 2024). "BET inhibition conferred a significant survival advantage in neuroblastoma models via regulating MYCN, providing a compelling rationale for developing BET bromodomain inhibitors in patients with neuroblastoma." (PMID 39273015, 2024). "To test this possibility, we induced MYCN expression in a neuroblastoma cell line with long telomeres that has a doxycycline inducible MYCN transgene, SKNMMMYCN." (PMID 38837897, 2024).
neuroblastoma (continued). "To interrogate the possibility that KAT2A and KAT2B are functionally redundant in this context, we used two MYCN-amplified neuroblastoma cell lines, KELLY and NB1, that depend on TADA2B but have high and low KAT2B expression, respectively." (PMID 38820154, 2024). "Further, the impact of pharmacologic degradation of KAT2A/KAT2B strongly correlated with the impact of TADA2B degradation, supporting the importance of the SAGA complex in maintaining MYCN-amplified neuroblastoma." (PMID 38820154, 2024). "In summary, our in vivo data demonstrate that GSK3326593 is a highly selective Prmt5 inhibitor, and that inhibition of Prmt5 in MYCN-dependent mouse neuroblastoma compromises the fitness and proliferation of tumour cells, resulting in their increased survival." (PMID 39313128, 2024). "Nevertheless, elevated ROS production in fast-proliferating neuroblastoma cells with high MYCN poses a threat to these cells when cyst(e)ine and/or selenocysteine are limiting and ferroptosis-triggering mechanisms are not suffciently counteracted." (PMID 38908072, 2024). "Neuroblastoma with MYCN amplification has been shown to be more resilient, suggesting a potential effect of MYCN gene amplification on the extracellular matrix of neuroblastoma." (PMID 38959634, 2024). "A study conducted on neuroblastoma cells revealed that Gln depletion results in increased radiosensitivity in non-MYCN amplified cell lines." (PMID 39199642, 2024). "DFMO treatment of neuroblastoma cell lines not only decreased the expression of MYCN, a proto-oncogene, but also resulted in reduced expression of LIN28." (PMID 38397415, 2024). "To assess this mechanism in the context of natural MYCN amplification and the chronically high levels of N-MYC expression that ensue, we performed loss-of-function experiments using the neuroblastoma cell line Kelly." (PMID 38748789, 2024). "A similar synergy was reported for γ-secretase-treated neuroblastoma cells that overexpress MYCN, and this was attributed, at least in part, to increased expression of the pro-apoptotic protein NOXA." (PMID 38984586, 2024). "pharmacological blocking of cystine transport, transsulfuration, and GPX4 inactivation led to tumour regression in a MYCN‐amplified neuroblastoma model." (PMID 39095325, 2024). "Deletion of one Runx1t1 allele in an independent Runx1t1 knockout mouse model is also sufficient to prevent MYCN-driven neuroblastoma development, and reverse ganglia hyperplasia, a known pre-requisite for tumorigenesis." (PMID 38992040, 2024). "Lastly, we validated that JMJD6 is essential to neuroblastoma growth in MYCN-amplified (BE2C) and MYC-overexpressed (SK-N-AS) xenograft models." (PMID 38488852, 2024). "Aurora kinase A (AURKA) plays a role in mitosis and stabilization of the MYCN protein in neuroblastoma." (PMID 38313265, 2024). "We stained a tissue microarray (TMA) consisting of tumor tissue from a cohort of 50 patients with stage 4 and MYCN-amplified neuroblastomas by immunohistochemistry." (PMID 38905335, 2024). "We performed calibrated chromatin immunoprecipitation sequencing (ChIP-seq) with an HA antibody in all three TADA2Bdeg, MYCN-amplified neuroblastoma cell lines." (PMID 38820154, 2024). "Conversely, TrkB is present in unfavourable neuroblastomas that often harbour amplification of the MYCN oncogene." (PMID 39389992, 2024). "Together our analyses identify a MYCN amplification dependent sensitivity of neuroblastoma cell-lines to GSK3203591." (PMID 39313128, 2024). "Consistently, neuroblastoma cell lines harboring DDX1-MYCN coamplification had elevated DDX1 protein and mRNA levels compared with those lacking DDX1 coamplifications or cells without MYCN amplification." (PMID 38197697, 2024).
neuroblastoma (continued). "Through its role as an intracellular antioxidant, GSH protects cells from increased oxidative stress, and in a subset of MYCN-amplified neuroblastoma cells, its disruption was reported to determine cell hypersensitivity to drugs." (PMID 38338881, 2024). "We also report survival distinctions based on intrinsic disorder of blood-sourced TRB sequences for MYCN amplified neuroblastoma, another tumor considered to be immunologically cold." (PMID 39519243, 2024). "MYCN amplification was identified as the first independent prognostic factor indicating adverse clinical outcomes in neuroblastomas, which is observed in approximately 20% of cases and accounts for about 40% of high-risk neuroblastomas." (PMID 38553589, 2024). "Crosstalk between BORIS and the Wnt signaling pathway in manipulating oncogenic networks has been shown to be involved in maintenance of stemness, regulation of metastasis and cellular proliferation in MYCN amplified the IMR-32 neuroblastoma cell line." (PMID 38929279, 2024). "Amplification of the MYCN oncogene, critically important for patient stratification, occurs in ~25% of neuroblastomas and can lead to amplification levels greater than 100-fold." (PMID 38992040, 2024). "A well-documented example of this is the amplification of the MYCN gene (located in 2p23-24) in approximately 20–30% of neuroblastoma cases." (PMID 38999925, 2024). "In 1983, additional studies revealed the amplification of MYCN sequences in eccDNA within neuroblastoma cell lines, establishing a connection between eccDNA and oncogene amplification, particularly in the context of cancer development." (PMID 39202666, 2024). "This susceptibility is intricately entwined with perturbation in cysteine metabolism, redox equilibrium, and iron regulation within neuroblastoma cells, particularly in the context of elevated MYCN activity." (PMID 38908072, 2024). "This process was demonstrated in a MYCN knockdown neuroblastoma model, in which decreased expression of several FAO-related enzymes (ETFA, HADHA, and HADHB) was detected." (PMID 37450923, 2024). "ATF4 and MYCN can synergistically upregulate ASCT2 expression, thereby promoting the invasive progression of MYCN‐amplified neuroblastoma cells." (PMID 38358002, 2024). "Previous studies have shown that amplification of the MYCN oncogene is detected in 20–30% of all detected cases of neuroblastoma." (PMID 38662139, 2024). "Beside xCT, the SELENOP receptor, LRP8, is required to protect MYCN-amplified neuroblastoma cells from ferroptosis." (PMID 38908072, 2024). "Although several studies employing mouse models of tumorigenesis support a tumor suppressor role for caspase-2, cancer-promoting role for caspase-2 has been reported for MYCN-driven neuroblastoma in a mouse model." (PMID 38429264, 2024). "Our study also identified that mitotic dysregulation was highly correlated with MYCN activity in established neuroblastoma." (PMID 37958555, 2023). "Much stronger associations were observed across multiple studies in this multivariate linear model, suggesting the transcriptional activation of MYCN expression in the NE state neuroblastoma tumors." (PMID 37255415, 2023). "The LDH levels, LEGmax, MTV and TLG can effectively predict the status of the MYCN oncogene and chromosome 1p36 in pediatric neuroblastoma and ganglioneuroblastoma." (PMID 37035169, 2023). "MYCN-amplified neuroblastoma cells are highly sensitive to ferroptosis, which also suggests a rather tumor-suppressive role of HIF2α in neuroblastoma." (PMID 37361539, 2023). "N-MYC, an important member of the MYC family, can directly accelerate the activation of GLS2 rather than GLS1 and promote oxidative glutamine metabolism in MYCN-amplified neuroblastoma cells." (PMID 37249801, 2023).
neuroblastoma (continued). "The v-myc avian myelocytomatosis viral oncogene neuroblastoma derived homolog (MYCN) is a common cancer driver gene in the most aggressive form of neuroblastoma and other cancers, such as medulloblastoma, ovarian, and prostate cancer." (PMID 36980710, 2023). "The genomic landscape of MYCN/IGF2BP1-induced neuroblastoma was analyzed by sWGS performed on AGM, TI, TIM and murine wildtype adrenal glands." (PMID 37246217, 2023). "This study aimed to explore the correlation between 18F-FDG PET/CT metabolism parameters and the status of the MYCN gene, chromosomal 1p and 11q in newly diagnosed pediatric neuroblastoma by reviewing our clinical experience." (PMID 37035169, 2023). "Our results suggested that ZNF436 was down-regulated with genetic 1p deletion or MYCN amplification and served as a favorable prognostic marker of neuroblastoma." (PMID 37904225, 2023). "Here, we characterized a molecular mechanism and translational significance of BAP1-mediated deubiquitination of MYCN in neuroblastoma." (PMID 37543638, 2023). "Aurora kinase A additionally protects from degradation MYCN, a major driver of oncogenesis in neuroblastoma." (PMID 37670947, 2023). "For example, in MYCN-amplified neuroblastoma cells, THZ1 was discovered to preferentially disrupt the global transcriptional regulation of MYCN." (PMID 37501079, 2023). "A first-in-class compound, HLB-0532259, has been developed that induces degradation of both Aurora-A and MYCN with high-selectivity and nanomolar potency in MYCN-amplified neuroblastoma cells." (PMID 37414143, 2023). "Most of these cancers lack significant MYCN expression, but MYCN is an oncogenic driver in pediatric neuroblastomas." (PMID 36768931, 2023). "Anaplastic lymphoma kinase (ALK) amplification is found in 2–3% of neuroblastoma and occurs frequently together with MYCN amplification." (PMID 37765276, 2023). "Kaplan–Meier curves of MYCN-amplified neuroblastoma PDXs showed a significantly longer overall survival in the treatment group, with more than 50% of mice alive at the end of the treatment period." (PMID 37874199, 2023). "A study that has been discussed already has observed that ODC1 expression is significantly higher in MYCN-positive neuroblastomas and there was a strong significant correlation between MYCN expression and ODC1 expression (r=0.80, p<0.0001)." (PMID 37206500, 2023). "For example, MYCN in MYCN-amplified neuroblastoma and the PAX3–FOXO1 and PAX7–FOXO1 fusion proteins in alveolar rhabdomyosarcoma promote tumour growth by hijacking tumour-type-specific CRC TFs15–19." (PMID 36658220, 2023). "More tellingly, SK-N-AS, a non–MYCN-amplified neuroblastoma cell line with corresponding low XIAP expression was also responsive to all three antagonists." (PMID 37874199, 2023). "The sensitivity of CT and MRI combined with serum LDH, NSE, CEA, and MYCN mRNA in the diagnosis of neuroblastoma was significantly higher than that of CT and MRI combined (P < 0.05)." (PMID 37592273, 2023). "Many research reports show that MYCN amplification is a biological indicator to measure the therapeutic effect and prognosis of neuroblastoma." (PMID 37592273, 2023). "Here, the authors perform whole transcriptome sequencing in 104 primary neuroblastomas and reveal the involvement of MYCN in regulating circRNAs." (PMID 37402719, 2023). "Some of the earliest evidence that MYCN contributes to neuroblastoma was demonstrated in transgenic mice overexpressing MYCN in neuroectodermal cells." (PMID 37414143, 2023). "The expression levels of ZNF436 were lower in neuroblastoma patients with MYCN amplification or age at diagnosis ≥ 18months, or with stage 4 neuroblastoma." (PMID 37904225, 2023). "The MYCN oncogene, present in neuroblastoma, induces replication stress by slowing the replication speed and amplifying fork stalling." (PMID 37508568, 2023).
neuroblastoma (continued). "This is evidenced by chromosomal misbalance reminiscent of human neuroblastoma in MYCN- as well as IGF2BP1-driven neuroblastoma mouse models." (PMID 37246217, 2023). "In line with this, we identified several differentially expressed RBPs in the MYCN-inducible cell model and neuroblastomas harboring MYCN amplifications." (PMID 37402719, 2023). "MYCN amplification occurs in approximately 20–30% of neuroblastoma patients and correlates with poor prognosis." (PMID 37958555, 2023). "Our study highlights the importance of MYCN regulating circRNAs in cancer and identifies molecular mechanisms, which explain their contribution to neuroblastoma pathogenesis." (PMID 37402719, 2023). "The cellular uptake and DNA-binding behavior of 191Pt-MYCN-PIP in cultured human neuroblastoma cells with different levels of MYCN gene amplification (amplified: Kelly; unamplified: SK-N-AS) were subsequently evaluated." (PMID 38004392, 2023). "RUNX3 was earlier shown to promote ubiquitination of MYCN in neuroblastoma and the Hedgehog pathway oncogenic transcription factor GLI1 in colorectal cancer cells." (PMID 37400551, 2023). "MYCN amplification (MNA) has been reported in approximately 25% of patients diagnosed with neuroblastoma, and MYCN amplification affected cell differentiation procedures." (PMID 37375824, 2023). "The reliance of aggressive (i.e., MYCN-dependent) neuroblastoma on OXPHOS points at first glance to the use of mitochondrial inhibitors to circumvent treatment resistance." (PMID 37414143, 2023). "Altogether, these results demonstrate that disulfiram downregulates KA2TA, decreasing histone acetylation and MYCN levels in neuroblastoma cells." (PMID 37777587, 2023). "A simple matter of time appears unlikely in view of genomic aberrations observed in other MYCN-driven neuroblastoma models within 80 d." (PMID 37246217, 2023). "MYCN amplification is one of the most powerful biological markers indicating poor prognosis in neuroblastoma." (PMID 37033189, 2023). "Our work provides evidence on the significance of circRNAs for neuroblastoma pathogenesis and extends knowledge about MYCN function, which implies broad relevance to cancers with an alteration of this oncogene." (PMID 37402719, 2023). "Oncogenic drivers like MYCN in neuroblastoma subsets continues to present a significant challenge owing to its strong correlation with high-risk metastatic disease and poor prognosis." (PMID 37274289, 2023). "As early as 2014, research showed that the TF MYCN upregulated the active transcriptional program of neuroblastoma cell oncogenes by promoting SE function." (PMID 37501079, 2023). "The associations of age of diagnosis, MYCN amplification, 1p deletion and ZNF436 expression in the prediction of the overall survival of neuroblastoma were further analyzed using multivariate cox regression assay." (PMID 37904225, 2023). "Recent research has shown that selective inhibition of the BET proteins led to potent downregulation of the MYCN genes in young patients with Neuroblastoma as well as various other solid malignancies." (PMID 37314524, 2023). "The sensitivity of CT and MRI combined with serum LDH, NSE, CEA, and MYCN in the diagnosis of neuroblastoma was notably higher than that of the three alone (P < 0.05)." (PMID 37592273, 2023). "The best characterized alteration in human neuroblastoma and the most important predictor of its poor prognosis is the amplification of a Myc-related gene, MYCN." (PMID 37444423, 2023). "Most (11/13; 85%) patients had stage 4 neuroblastoma at diagnosis; one patient had stage 3 neuroblastoma with MYCN amplification, and one was initially classified as stage 4S neuroblastoma but was then reclassified as stage 4 after a subsequent relapse." (PMID 37834840, 2023). "Our data demonstrate that targeting SELENOP uptake via LRP8 is a valuable strategy to efficiently disrupt GPX4 maintenance and trigger ferroptosis in cultured MYCN‐amplified neuroblastoma cells." (PMID 37435859, 2023).